PRL (prolactin)
Diseases named in the same sentence as PRL in open-access papers (continued):
Sharing a sentence is not in itself a finding about the gene and the disease.
Anxiety (continued). "In particular, anxiety is associated with lower oxytocin and prolactin which may inhibit the milk ejection reflex and subsequent breast milk production." (PMID 28936752, 2018). "Rotating night shifts too quickly may cause anxiety and decreased attentional performance, and may impact daytime prolactin levels after night shifts." (PMID 25091387, 2014). "We suggest that rotating night shifts too quickly may cause anxiety and decreased attentional performance, and may impact PRL levels during the day after night shifts." (PMID 25091387, 2014). "Moreover, we showed that inducing hippocampal DNA hypomethylation in young animals was sufficient to recapitulate the anxiety and cognitive deficits observed in aged animals and revealed a partial causal role of DNA methylation in the effects of PrL DBS on memory." (PMID 36818556, 2023). "Decreased serum PRL might cause anxiety in the first trimester of pregnancy." (PMID 30210449, 2018). "Alterations in prolactin levels early in pregnancy have been attributed to increased anxiety‐like behavior post‐partum." (PMID 40457890, 2025). "Secondly, dysregulation of the hypothalamic-pituitary-adrenal axis induces elevated serum cortisol and prolactin levels in patients with endometriosis, accounting for its regulation of stress, depression, and anxiety." (PMID 40130159, 2025). "Collectively, our study identified 2 anatomically segregated neuronal populations within AI that differentially modulate headache and comorbid anxiety via distinct projections to PrL and ovBNST, respectively." (PMID 41377021, 2025). "Studies have shown that the anti-anxiety drug buspirone increases PRL secretion through a dopaminergic mechanism." (PMID 40964426, 2025). "Excess prolactin can lead to decreased dopamine levels, contributing to depressive and anxiety symptoms." (PMID 41510476, 2025). "In this study on the mouse model of chronic headache and anxiety comorbidity after ISDN injections, we observed intensive c-fos expression in AI neurons and their downstream PrL and ovBNST, indicating their involvement in comorbid headache and anxiety." (PMID 41377021, 2025). "Stress, high levels of anxiety, depression, and other psychiatric disorders have been reported in infertile women with endometriosis as well as the impact on prolactin secretion of the medications used for the treatment of such disorders." (PMID 39407928, 2024). "Higher PRL levels were observed in the anxiety group compared to the non-anxiety group (P<0.001), in the insomnia group compared to the normal group (P<0.05), and in the low self-efficacy group compared to the medium and high self-efficacy groups (P<0.05)." (PMID 38572480, 2024). "Educational level, tumor size, number of visits, sleep quality, anxiety level, and self-efficacy level were found to be factors influencing PRL levels in patients with prolactinoma (P<0.05)." (PMID 38572480, 2024). "In summary, the correlations of PRL levels with anxiety, depression, sleep disturbances, and self-efficacy in prolactinoma patients have not been thoroughly investigated." (PMID 38572480, 2024). "In one small double-blind crossover study, treatment with DA led to improvements in depression, anxiety, wellbeing, and friendliness scores as prolactin levels declined." (PMID 38656635, 2024). "The purpose of this study was to explore the factors influencing PRL levels in patients with prolactinoma and to investigate the correlations between anxiety, depression, sleep, self-efficacy, and PRL levels." (PMID 38572480, 2024). "The GEE model showed that education level, tumor size, number of visits, sleep quality, anxiety level, and self-efficacy level were significantly related to PRL levels (P < 0.05)." (PMID 38572480, 2024). "The study demonstrated that compared to low anxiety behavior (LAB) rats, high anxiety behavior (HAB) rats exhibited increased basal and stress-induced PRL levels, possibly due to the association between inborn anxiety and HPA axis hyper-reactivity." (PMID 38572480, 2024).
Anxiety (continued). "Among factors assessing pituitary function (TSH, PRL, LH, FSH, ACTH), the concentration of LH (β: 0.123) and prolactin (β: 0.097) at the initial assessment were positive predictors of depression and anxiety scores, respectively." (PMID 39519542, 2024). "In women receiving prolactin-sparing antipsychotics, estrogen correlated negatively with depression/anxiety symptoms." (PMID 38995314, 2024). "PRL, best known for stimulating lactation, has additional roles in the central nervous system (CNS), which include effects on anxiety and depression as well as neuroprotection against inflammation." (PMID 38946666, 2024). "The mPFC, particularly the PrL area plays a key role in anxiety, memory, and social behaviors, and dysfunction of the circuitry between PrL pyramidal neurons and downstream brain areas causes autistic-like behaviors." (PMID 38503925, 2024). "Consistently, optogenetic suppression of the PrL-BLA circuit reversed anxiety-like behaviors, whereas activation of the PrL-l/vlPAG circuit attenuated hyperalgesia in mice with chronic pain." (PMID 36917193, 2023). "As reported in several previous studies where the initial raised serum PRL level decreased in subsequent samplings, we also observed that reduction of stress and anxiety with time and rest resulted in decreased PRL secretion." (PMID 36596817, 2023). "Lastly, specific knockdown of Tnfr1 in the PrL alleviated the anxiety-like behaviors in mice with chronic pain." (PMID 36917193, 2023). "Together, these results provide insights into the circuit and molecular mechanisms in the PrL for controlling pain-related hyperalgesia and anxiety-like behaviors." (PMID 36917193, 2023). "We provide multiple lines of evidence demonstrating that TNF-α in the PrL served as a trigger for elevated PrL-BLA circuit activity; this eventually was the cause of chronic pain–induced anxiety-like behaviors." (PMID 36917193, 2023). "Future investigations are required to define the contribution of TNF-α derived from distinct PrL cell types (individually or synergistically) to chronic pain-related anxiety-like behaviors." (PMID 36917193, 2023). "Further, we report a critical role of TNF-α signaling in the PrL in mediating chronic pain–induced anxiety-like behaviors." (PMID 36917193, 2023). "Blockade of TNF-α signaling in the PrL reverses chronic pain-related anxiety-like behaviors and synaptic deficits." (PMID 36917193, 2023). "We demonstrated that HFS PrL has DA-dependent effects on anxiety and hedonic-like activities in both DRN- and VTA-lesioned animals." (PMID 37296570, 2023). "All of these results point to a fundamental role of TNF-α signaling in the PrL in mediating anxiety-like behaviors during chronic pain." (PMID 36917193, 2023). "To further determine the underlying mechanisms mediating the elevated excitatory synaptic activity and anxiety symptoms in the chronic pain model, we collected PrL tissues from SNI and sham mice and subjected them to transcriptome analysis." (PMID 36917193, 2023). "In CRS mice, peripheral supplementation of SAM‐activated PrL neurons to suppress anxiety‐like behaviors." (PMID 35642952, 2022). "Then the hemodynamic status (blood pressure and pulse rate), level of serum cortisol, and prolactin and anxiety level (by using STAI-6) were measured." (PMID 35480569, 2022). "Behavioral phenotyping showed that disruption of m6A specifically in the PrL‐BLA circuit led to anxiety‐related phenotypes, suggesting the dependence of exercise intervention on m6A within this PrL‐BLA circuit." (PMID 35642952, 2022). "Ostoperative anxiety levels were significantly lower and postoperative prolactin levels were significantly higher for all groups." (PMID 35480569, 2022). "For example, it has been shown that the hormone oxytocin, that is strongly released during breastfeeding, improves physiological and psychological adaptation in mothers reducing cortisol, anxiety and increasing prolactin levels." (PMID 36081482, 2022).
Anxiety (continued). "The left mPFC seems to play a tonic role in the modulation of anxiety, since its functional inhibition, particularly in the PrL subarea, led mice to avoid the open arms of the EPM." (PMID 34497496, 2021). "From a biological point of view, the hypothalamic-pituitary-adrenal (HPA) axis can regulate various anxiety-related hormones, such as oxytocin, prolactin, and GABA." (PMID 34055993, 2021). "We found high anxiety levels and poor maternal care along with reduced serum prolactin and increased CORT levels in dams following maternal trauma (MT)." (PMID 33758173, 2021). "Whereas impaired AHN would increase anxiety, a higher PrL activity would be involved with positive copying behavior strategies." (PMID 34925362, 2021). "Anxiety is known to interfere with the release of oxytocin and prolactin, hormones that promote the milk ejection reflex." (PMID 34573866, 2021). "It is important to highlight that the initial aim of this study was to investigate the role of the dorsal region of the mPFC (i.e., Cg1 and PrL) in the modulation of avoidance/anxiety responses induced by local injection of CoCl2 in the left hemisphere." (PMID 34497496, 2021). "Conversely, the most downregulated genes observed were KCNJ13 and prolactin (PRL) in the mice that clustered in the high ‘anxiety’ phenotype, which implicate potassium voltage-gated family and oxytocin stimulation." (PMID 31819040, 2019). "Prolactin blood levels were positively correlated with the score obtained on an individual scale for quantifying the presence of anxiety-related behaviours through a physical and behavioural evaluation." (PMID 31547279, 2019). "Several studies have shown the involvement of the PrL in the regulation of anxiety and social behavior." (PMID 31084703, 2019). "Many lines of evidence suggest that PRL plays a protective role in anxiety-like, depressive-like and maternal behavior, although the precise role of PRL remains controversial." (PMID 31251738, 2019). "In males, low PRL has been found to be related to sexual dysfunction, metabolic syndrome, anxiety and depressive symptoms and lower general health." (PMID 30917615, 2019). "Optogenetic inhibition of PrL-projecting PVN OTergic neurons elicited anxiety-like behavior and decreased social preference in naive mandarin voles." (PMID 31084703, 2019). "The relationship between phobia, anxiety, and prolactin has been investigated by Pageat, 2007, however further research is needed for a better understanding of their possible links." (PMID 31277511, 2019). "A significant correlation was found between day-to-day changes in anxiety measured by questionnaires as well as by stress hormones, cortisol, and prolactin." (PMID 31277511, 2019). "In fact, cortisol, prolactin and day-to-day changes in anxiety indexes measured by questionnaires were found to be significantly correlated." (PMID 31547279, 2019). "There is a strong link between serotonin, pituitary hormones such as prolactin, and depression/anxiety." (PMID 29367404, 2018). "Otherwise, men with lower levels of prolactin showed the highest level of free-floating anxiety and related to psychobiological features such as anxiety symptoms and PE." (PMID 27619666, 2017). "These dismantled inhibitions to PrL would lead to an unbalanced accentuation of PrL-related activation of downstream limbic areas, and thus bias the fear regulation in favor of increased anxiety-like behavior." (PMID 26882036, 2016). "Further studies are needed to understand the mechanisms of action of PRL in the brain, and how this hormone modulates emotionality and anxiety at different developmental stages." (PMID 27065946, 2016). "The effects of PRL on anxiety and depressive behavior have been studied, but they differ depending on the species used and the physiological state." (PMID 27065946, 2016).
Anxiety (continued). "Prolactin contributes to a suppression of anxiety-related behaviours during pregnancy via binding to prolactin receptors, which are also known to bind the placental lactogens." (PMID 27523184, 2016). "Chronic ICV administration of PRL to ovariectomized E2-replaced female rats (used to simulate the endocrine status during pregnancy) was shown to reduce anxiety levels in the elevated plus maze." (PMID 27065946, 2016). "Increased basal and stress-induced levels of PRL were reported in male rats bred for high anxiety behavior (HAB) as compared to low anxiety behavior (LAB) rats." (PMID 27065946, 2016). "Several neuropeptides (neuropeptide Y, isotocin, urocortin 3, prolactin) showed consistent expression patterns with the alleviation of stress and anxiety when anxiety-related behavior was reduced with fluoxetine treatment." (PMID 23706039, 2013). "The downregulation of brain prolactin receptors increased anxiety-related behavior, demonstrating an anxiolytic effect of PRL in the brain." (PMID 24225037, 2013). "This hypothesis is substantiated by our findings that chronic ISDN injection-induced headache and anxiety are blocked by inhibition of ventral AI (vAI)-PrL and dorsal AI (dAI)-ovBNST circuits, respectively." (PMID 41377021, 2025). "More than 300 different biological functions have been described for prolactin, some of which are related to the central nervous system, including the stimulation of neurogenesis, modulation of stress responses, reduction of anxiety, transport of calcium and regulation of the immune system." (PMID 40806430, 2025). "Given that our RNAscope analysis revealed dense Cnr1 mRNA expression (encoding CB1R) in both PrL-projecting and ovBNST-projecting AI glutamatergic neurons, it is possible that eCB signaling within the vAI-PrL and dAI-ovBNST circuits regulates the comorbidity of headache and anxiety." (PMID 41377021, 2025). "Therefore, we should also pay attention to the effects of anti-anxiety drugs and anxiety itself on PRL." (PMID 40964426, 2025). "More than 300 different biological functions have been described for prolactin, some of which are related to the central nervous system, including the stimulation of neurogenesis, modulation of stress responses, reduction in anxiety, transport of calcium, and regulation of the immune system." (PMID 40507839, 2025). "However, the relationships between PRL and anxiety and depression in prolactinoma patients remain to be explored." (PMID 38572480, 2024). "PRL levels in patients with prolactinoma may be related to sleep quality, anxiety level, and self-efficacy level." (PMID 38572480, 2024). "PRL levels were higher in patients with anxiety, low self-efficacy, and sleep disorders." (PMID 38572480, 2024). "Our research has shown that prolactin levels in prolactinoma patients are associated with anxiety but not with depression." (PMID 38572480, 2024). "This increase in mean prolactin levels is in accordance with studies that showed that prolactin production can be increased through stimulation of the chest area or by avoiding stress and anxiety." (PMID 38813356, 2024). "Increased PRL levels result in higher levels of vasoinhibins, which could contribute to anxiety and depression behaviors." (PMID 38572480, 2024). "The PrL area plays an important role in the regulation of anxiety-like and social behaviors." (PMID 38503925, 2024). "Moreover, healthy lactating women with low anxiety—based on the Hamilton Anxiety Score, a questionnaire used to assess the level of anxiety—appeared to have high levels of prolactin." (PMID 38338751, 2024). "Prolactinoma patients often exhibit symptoms of depression, hostility, irritability, and anxiety, and stress may trigger neuroendocrine changes involving dopamine or serotonin, thus affecting the release of PRL." (PMID 38572480, 2024).
Anxiety (continued). "Pregnancy alters the regulation of GABA, norepinephrine, and prolactin as reflected in the cerebrospinal fluid (CSF) changes for these variables and could play a role in creating a vulnerability to anxiety and depression in this population." (PMID 37404586, 2023). "To examine whether activation of the PrL-BLA circuit could promote anxiety-like behaviors in mice with chronic pain, we injected the ChR2-expressing viral vectors into the PrL and implanted an optic cannula into the BLA." (PMID 36917193, 2023). "On the other hand, TNF-α accumulates in the PrL and further promotes the activity of BLA neurons by targeting PrLBLA neurons, which causes anxiety phenotypes and may further disturb pain perception." (PMID 36917193, 2023). "HFS PrL in both the CUS-susceptible and CUS-resilient animals significantly increased hedonia, reduced anxiety, decreased forced swim immobility, enhanced hippocampal DA and serotonin levels, and reduced corticosterone levels when compared with the respective sham groups." (PMID 37296570, 2023). "SNI surgery may serve as a trigger for inducing anxiety-like behaviors, which could be promoted by the activation of the PrL-BLA circuit." (PMID 36917193, 2023). "Moreover, the level of PRL was significantly correlated with heart rate and a wide range of self-reported measures of stress and psychopathology, including anxiety, hostility, and somatization." (PMID 36833950, 2023). "To investigate whether inhibition of the PrL-BLA circuit could reverse anxiety symptoms in mice with chronic pain, we injected halorhodopsin-expressing (NpHR-expressing) viral vectors into the PrL." (PMID 36917193, 2023). "In contrast, ample evidence suggests that the PrL became hyperactive at a high-anxiety state." (PMID 36917193, 2023). "Additionally, during late pregnancy, prolactin production is responsible for the low anxiety levels in lactating women, although anxiety can be experienced in women who have difficulty breastfeeding." (PMID 36141770, 2022). "Overall, 48% of the patients in this study experienced in that period mental disorders (anxiety, depression, and sleep disturbances), which may influence the level of prolactin." (PMID 35055804, 2022). "Thus, investigating the dopaminergic system activity via the measurement of blood PRL can help assess the chronic-stress responses and anxiety in dogs and follow-up their welfare states." (PMID 34573561, 2021). "LSD acutely induces marked alterations of perception and also moderately increases anxiety at 200 μg while additionally elevating autonomic stimulation and plasma markers of serotonergic activity and stress, including circulating prolactin and glucocorticoids." (PMID 34326773, 2021). "Additionally, we observed high anxiety levels and poor maternal care along with reduced serum prolactin and elevated serum CORT concentrations in dams following MT17." (PMID 33758173, 2021). "Day 3 hormonal analysis results for the female partner (including AMH, FSH, LH, estradiol (E2) and prolactin (PRL) levels) were similar between groups except the mean FSH level that was significantly elevated in case of moderate anxiety in comparison with severely anxious patients." (PMID 35233270, 2021). "We then evaluated whether knockdown of KIF3B within the PrL produced any deleterious effect on the animals by assessing general locomotion and anxiety-like behavior." (PMID 34749771, 2021). "Prolactin secretion during early pregnancy appears to be an important mediator of this increased neurogenesis with reduction of prolactin secretion in early pregnancy, reducing neurogenesis and leading to increased anxiety behavior and poor retrieval behavior of mice in a stressful environment." (PMID 34927138, 2021). "Low prolactin levels could also affect stress response since prolactin has shown to reduce anxiety behavior, modulate neurogenesis, and exert neuroprotection." (PMID 33228731, 2020).